RNU6-1015P (RNA, U6 small nuclear 1015, pseudogene)
Gene: Small nuclear RNA gene on chromosome X (112,919,132 to 112,919,230, forward strand). Ensembl gene ENSG00000252930.
Homologues: Orthologues: chimpanzee U6 (100% identical). Paralogues in human: RNU6-59P (76% identical), RNU6-1042P (75% identical), RNU6-1117P (75% identical), RNU6-38P (75% identical), RNU6-658P (75% identical), RNU6-1011P (74% identical), RNU6-1013P (74% identical), RNU6-1080P (74% identical), RNU6-1120P (74% identical), RNU6-1124P (74% identical), RNU6-1200P (74% identical), RNU6-1214P (74% identical), and 1287 more.